CD4 (CD4 molecule)
Diseases named in the same sentence as CD4 in open-access papers (continued):
Sharing a sentence is not in itself a finding about the gene and the disease.
kidney transplant (continued). "Citrus analysis showed a significant increase in the CD16+ CD4+ and CD16+ CD8+ T cell populations in the COP group compared to lung malignancies." (PMID 39860323, 2025). "Donor type significantly influenced the number of CD4+ and CD8+ T cells and Tregs in kidney transplant recipients." (PMID 39274306, 2024). "After thymectomy for the postnatal three days, regulatory CD4+CD25+ T cells were significantly reduced, and spontaneous prostatitis occurred." (PMID 37228599, 2023). "At 8 and 10 weeks, CD4+ T cells and CD8+ T cells were present in high numbers in the periparasitic area of liver hydatid cysts." (PMID 36046744, 2022). "Recently, a new subset of CD4 CD8 double positive T cells able to produce cytokines and cytolytic markers has been identified in the blood, airways and lung granulomas of Mtb infected cynomolgus macaques." (PMID 32117257, 2020). "CD4+ T cells produce IFN-γ in order to respond to advanced glycation end products and thus exacerbate inflammation in the diabetic kidney." (PMID 32283658, 2020). "After induction therapy of kidney transplant recipients with alemtuzumab, CD8+CD28− T cells recovered significantly faster than CD4 T cells." (PMID 30729139, 2019). "To examine the effect of BLT versus CsA on the frequency of circulating Tregs in kidney transplant patients, we first analyzed the expression of FOXP3 in total CD4+ T cells." (PMID 28316600, 2017). "The role of CD4+ T cells in murine liver IR has been well documented, and mice lacking CD4+ T cells are protected from liver IR injury." (PMID 39852164, 2025). "A recent study on SIV/TB co-infected non-human primates found that CD4+ T cells are rapidly depleted from the inner core and outer cuff of lung granulomas and the remaining CD4+ T cells display reduced motility in the GME." (PMID 36591229, 2022). "Aire− males develop non-lethal prostatitis because defective presentation of Aire−controlled self-peptides impairs negative selection in the thymus, decreases elimination of autoreactive CD4+ effectors and restricts development of tissue−specific Tregs27." (PMID 31653839, 2019). "Low baseline CD4 count and delay in CKD diagnosis (biological assessment only every 6 months) may have contributed to an increased mortality in our most fragile kidney patients, before eventual confirmation of the chronicity of their kidney disease." (PMID 31064340, 2019). "Flow cytometry revealed mis-homing of gut-primed immune cells (α4β7+ and CCR9 + CD4+) to the lungs and tracking bacteria via GFP- tagged fecal microbiome confirmed microbial translocation from the gut to the lungs which may contribute to lung inflammation." (PMID 40435188, 2025). "In a phase I trial of ex vivo expanded polyclonal recipient Tregs infused into patients receiving living donor kidney transplant, the adoptive transfer of these CD4 iTregs post-transplant was safe with no adverse effects or rejection up to two years post-transplant." (PMID 34575843, 2021). "In addition, the responsiveness to pepsin was only observed in CD4+ tonsil cells from pediatric patients with tonsil hypertrophy and not in CD4+ cells from adults with tonsillitis." (PMID 30408092, 2018). "VZV-reactive memory CD4+, but not CD8+ T cells also significantly increased upon in vitro stimulation by VZV infected dendritic cells in kidney transplant patients." (PMID 35935972, 2022). "In contrast, enlarged lymph node tumors were characteristic of the Gzmb-HBZ mice, but were not reported in the CD4-HBZ mice." (PMID 29050201, 2017).
Salmonella Infections (68 papers, 2008 to 2025). Infections with bacteria of the genus SALMONELLA. "EcNT@L mitigates nano PET‐associated Salmonella infection by correcting the dysregulated CD4+ T cell response and restoring the gut microbiota." (PMID 40167292, 2025). "Even though our patient was virologically suppressed on antiretroviral therapy, his low CD4 count likely predisposed him to Salmonella infection." (PMID 41178843, 2025). "Since humans require MHC class II-restricted T cell responses for efficient resolution of Salmonella infection, the susceptible mouse model is often used when studying the protective role of CD4 T cells against secondary infection." (PMID 27999159, 2016). "Genetic deletion of Mgat2 enhanced TCR signaling and reactivity of old-female CD4+ T cells and Mgat2-deficient T cells exhibited greater capacity to eliminate salmonella infection due to greater TH17 differentiation when compared to wild-type CD4+ T cells from old females." (PMID 38027254, 2023). "The prospect of predicting the burden of Salmonella infections based on the responses against these newly identified CD4+ T cell epitopes could lead to new diagnostic tools and reagents for tracking and analyzing Salmonella-specific T cell responses during Salmonella disease or after vaccination." (PMID 22912884, 2012). "Given Salmonella’s intracellular nature, recent research underscores the collaboration between CD4+ T-cells and B-cell responses in combating Salmonella infection, as demonstrated by our MEV simulations." (PMID 39792829, 2025). "In agreement with the strong decrease of IFNγ we found that the increase of IL-10 on CD4+ T cells in Salmonella infection is time dependent with the highest levels in iron fed Tim3−/− mice." (PMID 40939292, 2025). "P. copri is thought to increase Th17 inflammation, while H. parainfluenzae stimulates intestinal (IFN-γ) + CD4 + T cells, two mechanisms that play a key role in response to Salmonella infections." (PMID 40696437, 2025). "IL-10 neutralisation in iron loaded Tim3−/− mice resulted in improved Salmonella infection control and restorage of CD4+ mediated IFNγ formation." (PMID 40939292, 2025). "Our data revealed a significant expansion in the absolute number of CD8α+CD4+TCR1- cells in peripheral blood following Salmonella infection." (PMID 40438105, 2025). "CD4+ T lymphocytes play a major role in protective immunity during primary and secondary Salmonella infection." (PMID 35214684, 2022). "Although CD3-CD4- cells were the main source of IL-22 single cytokine production in cecum, CD3+CD4+ cells contributed nearly 20% of IL-22 production after Salmonella infection." (PMID 34566952, 2021). "Strikingly, mice from this eSPF barrier almost completely lost their ability to induce innate IL-17A and IL-22 producing CD4+ T cells upon Salmonella infection and cytokine production ability was successfully restored upon colonization with SFB." (PMID 34566952, 2021). "FACS analysis of cecal CD4+ T cells after Salmonella infection of eSPF+SFB mice revealed that ~70% of IFN-γ producing CD4 T cells did not secrete IL-17A or IL-22 indicating a classical Th1 phenotype." (PMID 34566952, 2021). "Hulk and 2W-Salmonella infections drove expansion of 2W1S-specific CD4+ T cells that were transcriptionally distinct by principle component analysis, with 22.3% of variation driven by infectious context." (PMID 34237106, 2021). "Following Salmonella infection, CD4 T cells are classically identified as the effector cells that expand and control infection." (PMID 34069796, 2021). "Taken together, these data demonstrate that presence of SFB alone is sufficient for the rapid production of IL-17A and IL-22 by CD4+ T cells after Salmonella infection." (PMID 34566952, 2021). "Together, these data suggest that, CD4+ T cells do not express IL-22 in steady state conditions in the intestine and that CD4+ T cells are a source of rapid or “innate-like” IL-22 responses in the cecum mucosa early after Salmonella infection." (PMID 34566952, 2021).
Salmonella Infections (continued). "Although robust initial activation of both CD8+ and CD4+ T cells occurs initially in response to Salmonella infection, we previously detected significant SteD-mediated suppression of CD4+ T cell activity at day 17 days post-oral inoculation." (PMID 34314469, 2021). "Along these lines, we were able to show that distinct members of the microbiota induced the enhancement of IFN-γ production by CD4+ T cells, which contributed to the resistance of mice against Salmonella infection." (PMID 34566952, 2021). "Appropriately, the CD4+ T cell subset was described to be the main effector subset in the defense of Salmonella infections." (PMID 34108960, 2021). "To determine the influence of SFB on the rapid CD4+ T cell response during Salmonella infection, specifically IL-22 production, we cohoused eSPF reporter mice with SFB monocolonized donor mice for 14 days." (PMID 34566952, 2021). "To examine the role of CCR6+ T cells in reponse to Salmonella infection, we investigated the percentage of CD4+/− CCR6+/− T cells in peripheral blood at 0, 24, and 192 h following S. Infantis challenge." (PMID 32093767, 2020). "To test this, we performed in vivo cytokine restimulation of 2W1S-specific CD4 T cells by intravenously administering 2W1S peptide to thymectomized and sham surgical mice 10 days post OmpC-2W1S Salmonella infection." (PMID 32722409, 2020). "It is known that control of both acute and persistent Salmonella infection relies on the presence of CD4 T cells." (PMID 32722409, 2020). "Most important, phenotypic analysis of T cells upon Salmonella infection demonstrated an increased expression of Sca-1 on CD4+ and CD8+ T cells from both mice strains." (PMID 29973931, 2018). "CD4+ T cells appear to play a vital role in mitigating Salmonella infection as mice compromised in CD4+ T cell responses show higher organ burden and succumb to the infection faster." (PMID 30452468, 2018). "Bacterial-specific Th1 immune responses including antibodies, CD4 T cells, cytokines are essential for the clearance of disseminated Salmonella infections, and Th1-promoting vaccines are likely to help prevent these infections." (PMID 28929089, 2017). "Although CD4+ T cells were thought to be the key producers of IFN-γ during Salmonella infections, it is well established that T cells and NK cells are important sources of this cytokine." (PMID 28749963, 2017). "The CD4+CD25+ cells were associated with suppressing the immune response and maintaining the Salmonella infection in the host." (PMID 29164140, 2017). "Against this, preservation of limited anti-viral function has been described for exhausted CD4 T cells, and similarly, chronic salmonella infection is controlled by late CD4 T cell responses." (PMID 26804905, 2016). "In conclusion, the positive selection induced by a Salmonella infection favors the generation of particular CD4 and CD8 SP T-cell clones, thus modifying the normal TCR usage frequency." (PMID 26417438, 2015). "Salmonella infection of inbred mouse strains induces a robust CD4+ T-cell response that is essential toward protective immunity to secondary infection." (PMID 25566242, 2014). "The strong understanding of both CD4 T cell and innate immune pathways during the response to Salmonella infection provides a strong foundation to further explore the potential interaction between these pathways." (PMID 25540644, 2014). "In a mouse model of Salmonella infection, a large proportion of CD4 T cells can be rapidly induced to secrete IFN-γ following intravenous injection of heat-killed bacteria." (PMID 25071779, 2014). "Detailed characterization of the protective T-cell response in salmonellosis is a pressing unmet need in light of the global burden of human Salmonella infections and the likely contribution of CD4 T cells to immunity against this intracellular infection." (PMID 24891088, 2014).
Salmonella Infections (continued). "Although CD4+ T cells are known as key players during Salmonella infection, the role of CD8+ T cell responses is less clear." (PMID 25484884, 2014). "Our results suggest that this is what occurred in the present in vitro study as IL-23 transcripts in CD1b+ L-DCs were detected after Salmonella infection, but possibly in insufficient quantities to promote IL-17 production by CD4+ T cells." (PMID 24223964, 2013). "To assess antigen presentation in the context of Salmonella infection we analysed I-Ak-dependent presentation of the model antigen hen egg lysozyme (HEL) by BMDCs to a CD4+ T-cell hybridoma expressing a HEL-specific TCR (3A9)." (PMID 23319341, 2013). "While culling of flagellin-specific CD4 T cells has been previously reported during Salmonella infection, we saw a steady expansion of total memory effector CD4 T cells over a time course of infection." (PMID 23754944, 2013). "Salmonella infection of murine DCs has been reported to inhibit presentation of antigen to CD4+ T cells." (PMID 23319341, 2013). "Whilst chronic typhoid carriers exhibit impaired humoral and cellular immunity, rapid priming of CD4+ T cells in mouse models of Salmonella infection was reported to elicit effective Th1 responses." (PMID 23319341, 2013). "Given the importance of CD4 T cells in the host defense against Salmonella infection, we first focused on the frequencies of two CD4 T cell subsets: TH1 and Tregs." (PMID 23754944, 2013). "We show that Salmonella infection influences MHC-II antigen presentation to CD4+ T cells by two distinct mechanisms." (PMID 23319341, 2013). "IL-17 is secreted by multiple cell types including Rorγt expressing CD4 T cells or TH17 cells which have also been shown to play a role in acute Salmonella infection." (PMID 23754944, 2013). "Compared to uninfected mice, Salmonella infection induces increased IL-6 responsiveness in naïve CD4 T cells but this responsiveness varied with the levels of fecal shedding." (PMID 23754944, 2013). "IFN-γ-producing CD4 T cells were detected seven days after Salmonella infection and were found to predominantly focus on flagellin, rather than TTSS effector epitopes." (PMID 22275869, 2012). "In conclusion, these data provide evidence that immunodominant CD4+ T cell responses that develop during virulent Salmonella infection are predictive for the disease activity." (PMID 22912884, 2012). "Given the importance of CD4+ T cells during Salmonella infection, we predicted genome-wide the MHC class II (H2 I-Ab) binding peptides encoded by S. Typhimurium strain LT2 and S. Typhi strain CT18 using optimized computer-based algorithms." (PMID 22912884, 2012). "To our knowledge, we provide here for the first time the identification of epitopes that are able to monitor CD4+ T cell responses during virulent Salmonella infection directly ex vivo." (PMID 22912884, 2012). "Numerous gene target studies have shown the importance of CD4+ activation in resistance to Salmonella infection." (PMID 23194372, 2012). "In conclusion, we demonstrate the feasibility of MHC class II binding predictions to identify CD4+ T cell responses during virulent Salmonella infection." (PMID 22912884, 2012). "The role of CD4+ T cells during Salmonella infection is likely two-fold: 1) direct effector cell activity and 2) providing help for B cells and CD8+ T cells." (PMID 22912884, 2012). "Since IFN-γ is a critical cytokine for controlling Salmonella infection, it is likely that CD4+ T cell derived IFN-γ plays a particularly important role." (PMID 22912884, 2012). "In summary, this study has identified new Salmonella I-Ab epitopes in T3SS effectors and used peptide-MHC tetramers and ELIPOT assays to simultaneously track multiple CD4 T cell responses during Salmonella infection for the first time." (PMID 22275869, 2012). "It has been shown that CD4+ cells are more important than CD8+ in resistance to Salmonella infection." (PMID 23194372, 2012).
Salmonella Infections (continued). "Our results indicate that polyfunctional CD4+ T cell responses, which develop during Salmonella infection, can predict important elements of disease activity." (PMID 22912884, 2012). "Next, we used ELISPOTs to examine the CD4 T cell response to oral Salmonella infection and closely monitored Th1, Th2, and Th17 responses to flagellin and TTSS effector proteins in mucosal and systemic tissues." (PMID 22275869, 2012). "The importance of CD4+ T cell activation was further demonstrated by the efficacy of therapeutic vaccination with the CD4+ T cell peptide epitopes during virulent Salmonella infection." (PMID 22912884, 2012). "To determine antigen-specific CD4 T cell induction, we adoptively transferred OVA-specific TCR-transgenic CD4 T cells one day prior to Salmonella infection." (PMID 23093937, 2012). "In the S. Typhimurium mouse model, CD4 and CD8 cells are critical to the development of protective immunity, and control of Salmonella infection involves prominent expression of interferon-γ by both CD4 and CD8 cells." (PMID 21666798, 2011). "Using these same techniques, we find similar numbers of FliC431–439-specific CD4+ T cells in naïve F1 mice prior to Salmonella infection." (PMID 20714351, 2010). "As predicted after Salmonella infection, the numbers of these FliC431–439-specific CD4+ T cells expand reaching ∼10-fold and 20-fold increased cell numbers day 5 and 37 post-infection, respectively." (PMID 20714351, 2010). "The precise mechanism by which colonic Tregs restrain cytotoxic CD4+ T cell responses during Salmonella infection remains unclear." (PMID 40924026, 2025). "Finally, given the heightened production of IFN-γ and granzymes by CD4+ T cells during Salmonella infection, we examined their role in exacerbating the immunopathology." (PMID 40924026, 2025). "Collectively, our findings demonstrate that Treg depletion during chronic Salmonella infection triggers an expansion of colonic cytotoxic CD4+ T cells that localize near the colonic epithelium, where they likely weaken barrier integrity, and exacerbate immunopathology and gut permeability." (PMID 40924026, 2025). "Based on our previous observations, we were interested whether blocking of IL-10 could rescue the production of IFNγ in CD4+ T cells and therefore be beneficial for the control of the Salmonella infection in conditions of iron overload in Tim3−/− mice." (PMID 40939292, 2025). "Taken together, Ascaris infection trends toward a modified type 2 response characterized by Th2 cells as seen in the blood and lung and dominant CD4 as well as CD8α Treg cells, while pigs responded to Salmonella infection with relatively prominent local Th1 and Th17 cell responses." (PMID 39140728, 2024). "In the same respect, CD4+CD69+ T cells expressing a high level of P2X7 have previously been characterized as TRMs that are key factors in promoting protection against the severe effects of Salmonella infection." (PMID 37457702, 2023). "CD4+ T cells might play a central role in acquired immunity against Salmonella infection and make an additional important contribution to both CD8+ T cell- and B cell-immunities." (PMID 35898510, 2022). "Since CD4+ T cells have been found to be important for the control of primary Salmonella infection and neutrophils are essential for the successful treatment of bacterial diseases with phages, we detected the percentage of CD4+ T cells and granulocytes in splenocytes." (PMID 36361621, 2022). "Notably, at early stages of Salmonella infection enhanced numbers of CD4+ T cells producing only IL-22 are observed in SFB colonized mice, which to our knowledge is the first report to observe microbiota modulation of Th22 cells in mice." (PMID 34566952, 2021). "The increased abundance of IL-17A-IL-22+ cells CD4+ T cells after Salmonella infection of eSPF+SFB compared to eSPF mice triggered the question of whether these SFB-induced cells are also detectable in steady state conditions." (PMID 34566952, 2021).